DGKZ (diacylglycerol kinase zeta)
Diseases named in the same sentence as DGKZ in open-access papers (continued):
Sharing a sentence is not in itself a finding about the gene and the disease.
tumor (9 papers, 2011 to 2025). "Expression of DGKZ was significantly up-regulated in OS tumor samples compared with normal bone tissue, and was associated with poor prognosis." (PMID 30662872, 2018). "We first confirmed that high DGKZ expression correlated with tumor progression and poor prognosis in patients." (PMID 35115500, 2022). "To further investigate the role of DGKZ in tumor metastasis, we constructed cells with stable overexpression and knockout of DGKZ in several TNBC cell lines." (PMID 35115500, 2022). "Importantly, GO and KEGG analysis displayed that differentially expressed proteins induced by silence of DGKZ were mostly enriched in autophagy or mitophagy, indicating that the functions of DGKZ on cell proliferation and tumor growth may be associated with autophagy or mitophagy." (PMID 33926342, 2021). "In the current study, we analyzed DGKZ expression in tumor tissues and adjacent normal tissues from CC patients and explored the role of DGKZ in in vivo tumor-bearing mouse models and in vitro CC cell lines." (PMID 33926342, 2021). "The high expression of DGKZ in tumor tissues from CC patients indicated the promising role of DGKZ in CC progression." (PMID 33926342, 2021). "After scarification, the averaged tumor weight of the control mice was extremely heavier than that in DGKZ-silenced group which presented suppressed tumor growth." (PMID 30662872, 2018). "In this study, DGKZ's expression was firstly investigated in OS tumor samples and correlated with poor outcome in OS patients." (PMID 30662872, 2018). "In vivo, DGKZ's knockout also suppressed xenograft tumor proliferation as determined by bioluminescence imaging and weight/volume measurements." (PMID 30662872, 2018). "Furthermore, BALB/c nude mice were injected subcutaneously with Lentivirus-sh-DGKZ-SiHa cells or Lentivirus-sh-NC-SiHa cells to analyze the influence of DGKZ silencing on tumor growth of CC in vivo." (PMID 33926342, 2021). "Inhibition of DGKZ suppressed tumor growth, which was evidenced both in vivo and in vitro." (PMID 33926342, 2021). "Previous data demonstrated that DGKZ was involved in tumor initiation and progression." (PMID 30662872, 2018). "Finally, univariate analysis was performed on 196 patients using a Cox regression model to explore the effects of different variables on DFS, indicating that tumor size, lymph node status, hormone receptor status, and DGKZ expression level were correlated with disease-free survival." (PMID 35115500, 2022). "Moreover, transwell migration assays suggested that the addition of LY2109761 could neutralize the enhanced tumor migration efficiency induced by DGKZ overexpression." (PMID 35115500, 2022). "In addition, Knockdown of DGKZ restrained tumor growth in tumor xenograft mice." (PMID 33926342, 2021). "Using healthy donor CD34+ cells as a reference, we detected overexpression of DGKA, DGKG, DGKD and DGKQ in tumor samples, while DGKH and DGKZ were unchanged." (PMID 37509516, 2023). "These trends are essentially in line with the TCGA results, except for the lack of evidence for increased expression of DGKE and DGKZ in tumor samples." (PMID 37509516, 2023). "The HCMDB results also indicated that DGKZ expression was significantly increased in the primary tumor tissues with metastasis compared with those without metastasis." (PMID 35115500, 2022). "For identifying the specific role of DGKZ in CC, DGKZ expression levels in 62 cervical tissues (31 tumor tissues and 31 adjacent non-tumor tissues from CC patients) were assessed using IHC." (PMID 33926342, 2021). "A number of genes demonstrated reduced copy number and expression in KRAS mutant tumours, including putative tumour suppressor genes (FOXO3, EXTL2, PPP2R1B), negative regulators of the receptor tyrosine kinase oncogenic pathways (PTPRK, DGKZ, NCAM1), and negative regulators of Ras (EPHB2)." (PMID 21385341, 2011).
cancer (8 papers, 2015 to 2024). A tumor composed of atypical neoplastic, often pleomorphic cells that invade other tissues. "Using The Cancer Genome Atlas dataset, a 5-CD8Gs risk model (KLRB1, FYN, IL2RG, FCER1G, and DGKZ) was constructed, which was verified in International Cancer Genome Consortium and gene expression omnibus datasets." (PMID 38489709, 2024). "For instance, elevated DGKZ expression contributes to increased Rho GTPase activation and the enhanced motility of metastatic cancer cells." (PMID 35115500, 2022). "DGKZ activates mammalian target of rapamycin complex 1(mTORC1), thus promoting cancer cell growth and survival." (PMID 33926342, 2021). "GO analysis indicated that DEPs triggered by DGKZ depletion mostly induced macro-autophagy and macro-mitophagy, which regulated cell apoptosis and cell cycle in most cancer development." (PMID 33926342, 2021). "Taken together, these data suggested that DGKZ might play an oncogenic role in multiple cancer types, making it worthy of further investigation." (PMID 35115500, 2022). "In addition, certain investigations have indicated that DGKZ is an oncogene facilitating cancer progression and development." (PMID 33926342, 2021). "Diacylglycerol kinase zeta (DGKZ) participates in cancer progression." (PMID 33926342, 2021). "Some of these AASEs affect genes that are not only associated with immunity but also play essential roles in inflammation (e.g., FN1 and HYAL2) and cancer oncogenesis (e.g., CTTN, FN1, and DGKZ)." (PMID 35752626, 2022). "The dysregulation of significant cancer-related genes (FAM83H, CXCL12, PITPNA, HMOX1, DGKZ, NR5A2, VMP1, and ID1) was confirmed by qRT-PCR." (PMID 36232920, 2022). "The regulation of DGKZ on downstream signal pathway in cancer cells is still not well-elucidated." (PMID 30662872, 2018).
DGKZ also shares sentences with these, for which no sentence is quoted: anorexia nervosa (1 paper); cervical tumor (1); colorectal cancer (1); depression (1); gastric cancer (1); Insulin resistance (1); invasive breast carcinoma (1); lung carcinoma (1); neurological diseases (1); renal clear cell cancer (1); spinocerebellar ataxia (1); T-cell lymphoma (1).